EPHA2 (EPH receptor A2)
Diseases named in the same sentence as EPHA2 in open-access papers (continued):
Sharing a sentence is not in itself a finding about the gene and the disease.
infection (59 papers, 2010 to 2026). The state of being infected such as from the introduction of a foreign agent such as serum, vaccine, antigenic substance or organism. "Another Eph receptor possibly involved in KSHV infection is EphA5 as transduction of an EphA5 (or an EphA4) construct was able to rescue infection in cells that were deficient for EphA2." (PMID 33430066, 2021). "The association of EphA2 with FAK was greatly decreased in infection with heparin pretreated KSHV which demonstrated the specificity of virus induced association of these signal molecules with EphA2." (PMID 23874206, 2013). "Compared to mock infection, EphA2-immunoprecipitates showed increased association with FAK, Src and PI3-K-p85 as early as 5 min p.i. which decreased by 10 and 30 min p.i.." (PMID 23874206, 2013). "In addition, the authors found that EphA2-deficient mice are less susceptible to infection with P. yoelii sporozoites, indicating that EPHA2 represents a potential target for HDT to block the entry of parasites in hepatocytes." (PMID 35669122, 2022). "Interestingly, a reduction of P. yoelii liver stage burden was observed in Epha2(-/-) mice, associated with a delayed onset of blood stage infection." (PMID 29975762, 2018). "First, a functional connection of P36 with EphA2, a host cell receptor involved in hepatocyte susceptibility to infection and formation of the PVM, was proposed following the observation that signaling of EphA2 upon interaction with its natural ligand EphrinA1 was disrupted in the presence of P36." (PMID 30547015, 2018). "Loss of EphA2 function reduces the induction of these signals, virus entry and infection." (PMID 23874206, 2013). "NR4A1 has been identified as an important regulator of immune and inflammatory responses, while the EphA2 gene has been shown to interfere with the response to infection in studies of host interactions with Mycobacterium tuberculosis." (PMID 39202454, 2024). "We observed an infection-specific increase in phosphorylation of EphA2 and Akt, as well as an infection-specific increase in c-Fos protein levels." (PMID 38427950, 2024). "To determine if increasing these receptor levels would improve infection rates in our ectopic huLiver model, we generated a HC-04 cell line with higher expression of both EphA2 and CD81; HC-04 EphA2High CD81 High." (PMID 36928885, 2023). "Our research suggests that EphA2 mediates the infection of HCMV by interacting with glycoproteins gH/gL/gO displaying on the surface of HCMV virion." (PMID 37146061, 2023). "Both mRNA and total protein levels of EPHA2 (total-EPHA2) were increased upon infection in human BECs." (PMID 36297233, 2022). "Receptor tyrosine kinases, including EPHA2, have been widely used by many human pathogens for successful infection, intracellular survival and replication within the host cell." (PMID 36297233, 2022). "It is evident from our results that the intracellular survival of uropathogen is dependent on EPHA2 signaling, as inhibition of EPHA2 signaling pre- and post-infection significantly reduced the infection in BECs." (PMID 36297233, 2022). "Further investigation is required to validate if EPHA2 can serve as an entry receptor during early infection." (PMID 36297233, 2022). "Since our EPHA2 knockdown study convincingly reduced the uropathogens infection, we made use of the approved EPHA2 inhibitors such as dasatinib and ALW-II-41-27." (PMID 36297233, 2022). "The elevated EPHA2 phosphorylation levels likely parallel the increased total EPHA2 levels following infection." (PMID 36297233, 2022). "It was found that surface expression of several recombinant fragments of EphA2 enhanced the parasite infection rate, thus establishing its role in P. vivax infection." (PMID 36513700, 2022). "In our study, we investigated and demonstrated a functional role of the extracellular domain of EphA2 in P. vivax liver-stage infection, using an in vitro culture system of the hepatic HC-04 cell line." (PMID 36513700, 2022).
infection (continued). "Infection of BECs with seven different uropathogens enhanced the expression levels and activation of EPHA2." (PMID 36297233, 2022). "To rule out a possible decrease of dissemination out of the bloodstream, we collected kidneys from WT and Epha2–/– mice 12 h post infection and enumerated fungal burden." (PMID 36138043, 2022). "With the progression of infection, among the many host-signaling pathways utilized by uropathogens, we identified EPHA2 as one such signaling platform through which they achieve successful infection." (PMID 36297233, 2022). "This would be in agreement with observations that EphA2 is upregulated during infection by the ERK pathway." (PMID 33468693, 2021). "Previously, we found that infection of oral epithelial cells with viable C. albicans induces sustained phosphorylation of both EphA2 and EGFR, leading to the secretion of proinflammatory mediators." (PMID 33471869, 2021). "As predicted by the in vitro data, treatment with gefitinib reduced the phosphorylation of both EGFR and EphA2 in CD45- EpCam+ cells after 1 d of infection." (PMID 33471869, 2021). "EphA2 is essential for viral entry, as knockdown or deletion of EphA2 abolished the infection of endothelial cells." (PMID 33430066, 2021). "This suggests that other events must precede the infection to allow accessibility of EPHA2 such as chronic inflammation or tissue damage which is known to alter the localization/expression of cellular receptors." (PMID 33596248, 2021). "The results show that CT2A cells have high basal Epha2 expression and that C170 infection further shifted the EphA2 surface expression based on fluorescent intensity." (PMID 34599026, 2021). "We treated mice beginning at day 4 post-infection with a recombinant EphA2-Fc protein which has the potential to act as a decoy receptor through binding soluble and cell-bound ephrin-A ligands and preventing their binding to cell-bound EphA2." (PMID 31999807, 2020). "Infection of both cell lines with H. pylori strains 60190 or 26695 induced downregulation of EPHA2 protein levels for long periods of time post-infection, as evaluated by Western blot, which was confirmed by immunofluorescence." (PMID 32102381, 2020). "This indicates that ephrin-A1 ligands can be shed in an EphA2-independent manner from other organ sites and cell types during infection, likely through interactions with other EphA receptors that ephrin-A1 is able to bind." (PMID 31999807, 2020). "All mutants and the wild-type strain were equally efficient in inducing EPHA2 downregulation 24 h post-infection, demonstrating that H. pylori-induced EPHA2 receptor downregulation is independent of these factors." (PMID 32102381, 2020). "Since the majority of pRBCs and CD8+ T cells are known to adhere to the brain microvascular endothelium on the luminal surface of blood vessels during ECM, we sought to determine the impact of PbA infection specifically on endothelial-expressed EphA2." (PMID 31999807, 2020). "Using a phosphotyrosine ELISA for EPHA2, we found that PP2 and Dasatinib inhibitors significantly decreased tyrosine-phosphorylation of EPHA2 at 1 h post-infection (2.6×- and 3.6×-reduction for PP2 and Dasatinib, respectively; p < 0.0001)." (PMID 32102381, 2020). "To assess if the decrease in EPHA2 protein expression upon infection was due to transcriptional regulation, we determined the relative expression of EPHA2 mRNA levels by real time quantitative PCR (RT-qPCR)." (PMID 32102381, 2020). "Flow cytometry showed increased infection of KSHV in the presence of either EphA2 or EphA4 and higher levels of fusion when both EphA2 and EphA4 were transfected." (PMID 30782663, 2019). "It was notably shown in these studies that EphA2 specifically bound to gHgL and antibodies against EphA2, or EphA2 inhibition, blocked EC infection." (PMID 31766729, 2019). "Transfection of the double-knockout cells with EphA2 or EphA4, and especially both EphA2 and EphA4, rescued infection." (PMID 30782663, 2019).
infection (continued). "In the current studies, we have found that EphA4 promotes KSHV glycoprotein H/glycoprotein L (gH/gL)-mediated fusion and infection better than does ephrin A2 (EphA2) in HEK293T cells, indicating that EphA4 is a new KSHV entry receptor." (PMID 30782663, 2019). "The knockout of EphA2 significantly reduced infection, but the defect was rescuable by ephrin receptors other than A2." (PMID 31752107, 2019). "Knockout of both EphA2 and EphA4 greatly decreased fusion and infection of KSHV, while overexpression of EphA2 and EphA4 alone or together rescued the fusion and infection of EphA2-EphA4 double-knockout cells." (PMID 30782663, 2019). "To confirm EphA4 is important for KSHV fusion and infection, we generated EphA2 and EphA4 single- and double-knockout cells." (PMID 30782663, 2019). "Fusion and infection of KSHV were rescued in the EphA2-EphA4 double-knockout cells upon overexpression of EphA2 and/or EphA4." (PMID 30782663, 2019). "At the same time, intracellular bacterial load was reduced twofold at 2 and 6 hours post-infection in the EPHA2 knockout cell line, suggesting that the EPHA2 receptor is important for the successful internalization of S. aureus inside host cells." (PMID 30890742, 2019). "The level of infection in EphA2-expressing cells was just above background levels, in contrast to the EphA4-expressing cells, in which the level of infection was higher." (PMID 30782663, 2019). "When EphA2 and EphA4 were individually transfected into the double-knockout cells, infection with KSHV was partially rescued compared to levels observed in HEK293T cells." (PMID 30782663, 2019). "We next measured the impact of EphA2 silencing on CD81-dependent infection using GFP-expressing P. yoelii parasites (PyGFP)." (PMID 29975762, 2018). "As p36/p52-knockout sporozoites do not productively invade cells, these results argue against a functional interaction between EphA2 and P36 (or P52) for host cell infection." (PMID 29975762, 2018). "Following infection with PbGFP sporozoites, cells were recovered at 24 hours post-infection, labeled with anti-EphA2 or anti-CD81-antibodies and analyzed by FACS." (PMID 29975762, 2018). "The dramatic inhibition of KSHV and RRV wt infection demonstrated by specifically targeting the Eph interaction or after EphA2 knockdown or knockout is similar in extent to what we observed using a soluble decoy receptor block." (PMID 29432452, 2018). "The reduction in EPHA2 was still evident following infection with either E4orf3-deleted virus or E4orf6-deleted virus, while from transfection studies, E1B-55k/E4orf6 was involved in the reduction of EPHA2." (PMID 28631589, 2017). "The receptor tyrosine kinase EphA2 is also critical for hepatocyte infection, at least in part by engaging the parasite protein P36." (PMID 29201016, 2017). "Weconfirmed that AR can co-immunoprecipitates with activated EphA2 during KSHV primary infection, along with Src." (PMID 28957431, 2017). "Blocking of EphA2 inhibited productive infection of LC by 70.1% by 72 h postinfection, while blocking with the antilangerin MAb or the combination of the polyclonal anti-EphA2 Ab and antilangerin MAb inhibited infection by 58% and 99.2%, respectively." (PMID 28768873, 2017). "Interfering with pAkt signaling by modulating EphA2 levels also influenced Ctr primary and progeny infection." (PMID 25906164, 2015). "During this phase of infection, EphA2 levels remain largely unchanged indicating that post-translational modification by phosphorylation is the main mechanism of activation." (PMID 25906164, 2015). "We show the recruitment of active EphA2 to the inclusion membrane during the mid-phase of the infection cycle indicating that EphA2-mediated signaling occurs at the cytosolic side of the inclusion membrane." (PMID 25906164, 2015). "The amount and phosphorylation of EphA2 increased during Ctr infection in HeLa, HUVEC and also in Fimb cells, demonstrating that this is not a cell line specific effect." (PMID 25906164, 2015).
infection (continued). "EphA2 overexpression or EphA2 silencing changed the progeny infection by approximately 48% (increase during overexpression) and 37% (decrease during knockdown), respectively." (PMID 25906164, 2015). "We then also investigated the role of internalized EphA2 for apoptosis resistance induced by infection with Ctr-serovar D. EphA2 silenced cells upon 16 h p.i. were sensitized for TNF-α/CHX-induced apoptosis determined by PARP cleavage." (PMID 25906164, 2015). "The interaction was further verified by microscopy showing the co-localization of EphA2 with activated PI3K after Ctr infection." (PMID 25906164, 2015). "Pretreatment of cells with DA for 1 h followed by 24 h of infection inhibited EphA2 activation and strongly affected Ctr infection." (PMID 25906164, 2015). "The EphA2 overexpressing cells infected for 24 h were further re-infected with new EB for 4 h (re-infection assay)." (PMID 25906164, 2015). "The levels of activated Akt and Ctr infection were clearly affected in cells expressing EphA2K645R compared to full length EphA2." (PMID 25906164, 2015). "We then investigated where the increased and activated EphA2 is located in the infected cell during the mid-phase of Ctr infection." (PMID 25906164, 2015). "Binding to EPHA2 follows KSHVs initial interaction with integrins, leading to EPHA2 phosphorylation, coordinated integrin-associated downstream signaling and endocytosis, which enables KSHV entry and subsequent infection." (PMID 26008702, 2015). "Since surface EphA2 is required for Ctr adherence and invasion, we next investigated the activation of EphA2 upon Ctr infection." (PMID 25906164, 2015). "This strategy did not only inhibit the Ctr-induced EphA2 activation but also reduced the Ctr infection in a dose-dependent manner." (PMID 25906164, 2015). "The quantification by counting the green fluorescent protein- (GFP-) positive cells showed that ~85% of cells on average were overexpressed by EPHA2 and its missense mutants 72 h after infection." (PMID 26664742, 2015). "In line with receptor activation by Ctr infection, we observed an increased EphA2 phosphorylation, reaching a 9-fold increase as early as 15 min p.i.." (PMID 25906164, 2015). "We found EphA2 activation not only at the cytoplasmic membrane during the initial phase of infection but also surrounding the endocytosed bacteria, indicating that this surface receptor continues to activate the PI3K pathway from within the infected cells." (PMID 25906164, 2015). "Interfering with binding of C. trachomatis serovar L2 (Ctr) to EphA2, downregulation of EphA2 expression or inhibition of EphA2 activity significantly reduced Ctr infection." (PMID 25906164, 2015). "Despite the depletion of EphA2 from the cell surface, Ctr infection induces upregulation of EphA2 through the activation of the ERK pathway, which keeps the infected cell in an apoptosis-resistant state." (PMID 25906164, 2015). "We then made use of the RTK inhibitor dasatinib (DA) to further investigate the role of the kinase activity of endogenous EphA2 for Ctr infection." (PMID 25906164, 2015). "Consistently, the total and activated levels of EphA2 increased with increasing infection times (14, 20 and 36 h) as was detected by immunoblot analysis of cells infected with viable, but not heat-killed bacteria." (PMID 25906164, 2015). "We, therefore, investigated the role of the MAPK (Ras/Raf/MEK/ERK) and PI3K pathways in upregulation of EphA2 during Ctr infection." (PMID 25906164, 2015). "We, in addition, showed that the infection-induced ERK signaling is required for EphA2 upregulation and activation." (PMID 25906164, 2015). "Number of inclusion in both primary (18% reduction) and secondary infection (43% reduction) as well as the size of the inclusion in primary infection (40% reduction) were significantly affected upon silencing EphA2 expression." (PMID 25906164, 2015).
infection (continued). "The strong and long-lasting upregulation of EphA2 expression leading to its accumulation around the inclusion implied that infection-induced signaling pathways are involved." (PMID 25906164, 2015). "Surface EphA2 expression was similar at three different time points of Ctr infection (14, 20 and 26 h p.i.)whereas permeabilised-infected cells (20 and 26 h p.i.)displayed a clear increase of intracellular EphA2 levels." (PMID 25906164, 2015). "CIB1 depletion by shRNA significantly reduced KSHV-induced bleb formation, activation of EphA2, Src, and Erk1/2, virus entry by macropinocytosis, productive trafficking, and infection." (PMID 24550731, 2014). "More importantly, knocking down CIB1 significantly inhibited KSHV entry and de novo infection due to a substantial reduction in EphA2 induced signal amplification." (PMID 24550731, 2014). "KSHV bound integrins αVβ3 and α3β1 translocate to the LRs leading into the interaction with EphA2, macropinocytosis and infection of HMVEC-d cells." (PMID 24550731, 2014). "Taken together, these studies demonstrated that KSHV induced differential regulation of cellular signaling via EphA2 and c-Cbl is crucial for endocytosis during de novo infection." (PMID 24550731, 2014). "While deletion of CagA abolished the infection-induced increase in EPHA2 phosphorylation, deletion of the T4SS led to an increase in phosphorylation above the cut-off, reminiscent of a compensatory effect of CagA on the effect of the T4SS alone." (PMID 25101063, 2014). "Infection increased the association of CIB1 with LRs, and CIB1 was associated with EphA2 and KSHV entry associated signal molecules such as Src, PI3-K, and c-Cbl." (PMID 24550731, 2014). "In conjunction with this we also observed ≥80% reduction in the punctate nuclear staining of LANA-1 at 48 h post infection (p.i.)in EphA2 shRNA transduced HFF cells compared to control sh-RNA cells (C1 and C2)." (PMID 23874206, 2013). "Taken together, our results clearly demonstrated that c-Cbl dependent EphA2 polyubiquitination is essential for clathrin mediated entry of KSHV in HFF cells which results in a productive infection leading to establishment of latency." (PMID 23874206, 2013). "EphA2 is associated with KSHV as well as integrin α3β1 and αVβ3 early during infection, suggesting one role of EphA2 as a scaffold protein for recruiting entry and signaling complex for a successful infection." (PMID 23420076, 2012). "Since our results demonstrate that the pretreatment of epithelial cells with RNA interference or inhibitor targeting EPHA2 prior to infection significantly reduced intracellular bacterial survival, the EPHA2 receptor can be a critical factor during the early phase of uropathogen infection." (PMID 36297233, 2022). "Thus, we used the viral supernatant produced by the infection of 293T cells with the packaging plasmid to infect SiHa cells and established a stable EphA2 knockdown strain (sh-EphA2)." (PMID 36478746, 2022). "Because the transient transfection of EphA2 extracellular domains could enhance P. vivax infection at 20–30% transfection efficiency, we thought that higher infection rates could be obtained through stable transfection." (PMID 36513700, 2022). "Many studies previously identified EPHA2 as being upstream signaling of PI3K-Akt in certain pathogen infections; therefore, we hypothesized that uropathogens might also utilize EPHA2 signaling." (PMID 36297233, 2022). "Since we observed augmented expression and activation of EPHA2 in BECs infected with uropathogens, we next questioned whether the downregulation of EPHA2 affects infection and colony formation." (PMID 36297233, 2022). "Several human pathogens manipulate host EPHA2 signaling during infection." (PMID 36297233, 2022).